OR2V1 (olfactory receptor family 2 subfamily V member 1)
Description:
Odorant receptor.
Synonyms: OST265; OR2V1P
Tractability: Antibody: UniProt places it where antibodies can reach, with medium confidence; UniProt predicts a signal peptide or a membrane-spanning region; its Gene Ontology location is reachable by antibodies, with medium confidence.
Gene: Protein-coding gene on chromosome 5 (181,123,122 to 181,131,169, reverse strand). Ensembl gene ENSG00000185372.
Subcellular location: Cell membrane
Pathways (Reactome):
Sensory Perception: Expression and translocation of olfactory receptors
Gene Ontology:
Molecular function: olfactory receptor activity; G protein-coupled receptor activity
Biological process: detection of chemical stimulus involved in sensory perception of smell; G protein-coupled receptor signaling pathway
Cellular component: plasma membrane; membrane
Genetic constraint (gnomAD): Loss-of-function variants: 18 observed, 15.21 expected, observed/expected ratio (o/e) 1.18, 90% interval 0.82 to 1.72. The upper end of that interval is the gene's LOEUF score, 1.72, which puts it in group 6 of 6, group 1 being the genes least tolerant of losing a copy. Missense variants: 359 observed, 400.63 expected, observed/expected ratio (o/e) 0.9, 90% interval 0.82 to 0.98. Synonymous variants: 144 observed, 151.54 expected, observed/expected ratio (o/e) 0.95, 90% interval 0.83 to 1.09.
Homologues: Orthologues: chimpanzee OR2V1 (97% identical), mouse Or2v1 (88% identical), rat Or2v1 (88% identical), pig OR2V1 (85% identical). Paralogues in human: OR2V2 (87% identical), OR2T33 (55% identical), OR2M4 (54% identical), OR2M5 (54% identical), OR2T12 (54% identical), OR2T8 (54% identical), OR2M2 (53% identical), OR2M3 (53% identical), OR2Z1 (53% identical), OR2T1 (52% identical), OR2T2 (52% identical), OR2T35 (52% identical), and 80 more.